IL1B (interleukin 1 beta)
Diseases named in the same sentence as IL1B in open-access papers (continued):
Sharing a sentence is not in itself a finding about the gene and the disease.
colitis (continued). "In contrast to their CX3CR1hi counterparts, as we show here, cells within the CX3CR1int compartment are actively proinflammatory, expressing much higher levels of mRNA for proinflammatory mediators such as IL-1β, iNOS, IL-23, and IL-12 during H. hepaticus colitis than their control counterparts." (PMID 29203542, 2018). "Additionally, the production of TNF-α and IL-1β is significantly inhibited after oral administration of LycogenTM in mice with DSS-induced colitis or renal injury." (PMID 29642620, 2018). "Indeed, although several pre-clinical studies in animal models of colitis showed that the inhibition of IL-1β decreased tissue inflammation and necrosis, others found few or no beneficial effects following IL-1β inhibition." (PMID 30559669, 2018). "Additionally, inhibition of IL-1β activity with a receptor antagonist has been shown to decrease intestinal inflammation in a murine model of colitis." (PMID 30524506, 2018). "The therapeutic effect on endoscopic signs of colitis was accompanied by diminished expression levels of proinflammatory mediators within colon tissues as we detected reduced amounts of Il1b, Tnf, Csf2, and Ifng transcripts in anti-IL-7R/anti-GM-CSF- compared to control antibody-treated mice." (PMID 29910804, 2018). "It follows from this that mice with PTPN22-deficiency manifest decreased NLRP3 inflammasome activity (and decreased IL-1β production) upon exposure to an inflammatory stimulus and therefore exhibit increased DSS-colitis in the same manner as do mice with frank NLRP3-deficiency." (PMID 30455704, 2018). "We argue for a much more important role of IL-1β in development of colitis compared to IL-6." (PMID 30315268, 2018). "The induction of colitis significantly increased the mucosal concentration of IL-1β in the colon." (PMID 29865176, 2018). "However, after treatment with sulfasalazine and TRYP, the levels of IL-6 and TNF-α decreased greatly comparing with the colitis group, while the levels of IL-1β and IL-10 changed insignificantly." (PMID 29724065, 2018). "Moreover, mice with a Rac1 conditional deletion in neutrophils and macrophages are resistant to DSS-colitis, showing reduced neutrophil migration and reduced levels of IL1β and KC." (PMID 29566748, 2018). "Thus, although there were diverse myeloid sources of IL-1β during DSS colitis, monocytes were the most responsive and prominent IL-1β+ population, undergoing the greatest numerical and per cell changes in this setting." (PMID 30542349, 2018). "Indeed, M2-associated genes (Arg1, IL-10, Fizz1, and Mrc1) were increased and M1-associated genes (IL-1β, IL-6, IL-12, and TNF-α) were decreased in colons of DSS colitis miR-155−/− mice." (PMID 29774026, 2018). "Pro-inflammatory Tnf, Ifnγ, Il6 and Il1β mRNA expression levels were increased in colitis." (PMID 30315190, 2018). "IL-1b and IL-6 production are increased in Nrf2−/− mice with dextran sulfate-induced colitis." (PMID 30180849, 2018). "We show that in murine colitis, colon monocytes represent the key myeloid source of IL-1β." (PMID 30542349, 2018). "Recently a human mucosa colitis model was developed using TNFα and IL-1β." (PMID 30127744, 2018). "Proinflammatory cytokines TNFα and IL-1β (each 10 ng/mL) were used to induce colitis in mucosal strips, and the effects of Panx1 and P2X7R on cytokines-induced tissue damage were determined in the presence of the Panx1 channel blocker 10Panx1 (100 μM) and P2X7R antagonist A438079 (100 μM)." (PMID 30127744, 2018). "Moreover, in hypophysectomized rats, administration of ghrelin failed to affect serum levels of GH or IGF-1, as well as the healing rate of colitis, mucosal cell proliferation, and mucosal concentration of IL-1β, or activity of myeloperoxidase." (PMID 28538694, 2017). "Likewise, we also showed that IL-1β and IL-6 gene expression were significantly down-regulated at day 31 in experimental colitis mice when injected with TMSC[x4]." (PMID 28854223, 2017).
colitis (continued). "For instance, administration of cocoa FGM-derived polyphenols to DSS-induced colitis mice led to a partial but significant abrogation of intestinal length reduction, while levels of TNF-α and IL-1β significantly dropped in inflamed colon homogenates in comparison to untreated colitis animals." (PMID 28649251, 2017). "Finally, treatment with TMSC[x4] significantly reversed the mRNA levels of IL-1β and IL-6, although expression of all pro-inflammatory cytokines tested was induced in colitis mice." (PMID 28854223, 2017). "In addition to a regulatory effect on cytokines, CHOP can promote the infiltration of macrophages, induce ROS and IL-1β production, or enhance apoptosis of epithelial cells, thus leading to the development of colitis." (PMID 29118753, 2017). "In line with above results, GLP-1 in sterically stabilized phospholipid micelles (GLP-1-SSM), showing a long half-life and resistant to DPP-4, markedly alleviated the development of DSS-induced mice colitis by reducing the expression of pro-inflammatory cytokine IL-1β." (PMID 29270177, 2017). "A large amount of evidence indicates that animals subjected to TNBS-induced colitis suffer from diarrhea, weight loss, disorganization of the colon mucosa and sub-mucosa, and significantly increased MDA content, MPO activity, TNF-α and IL-1β." (PMID 28056930, 2017). "Furthermore, the expression of proinflammatory mediators such as TNF-α, IL-1β, IL-6 and iNOS mRNA in the colons of WT colitis mice was markedly upregulated on day 7 and significantly higher than those of p85α+/− colitis mice." (PMID 28733636, 2017). "Furthermore, similar antioxidant MitoQ mitigated symptoms of experimental colitis, which is governed, at least partially, by the prevention of IL-1β and IL-18 release." (PMID 29158874, 2017). "Indeed, although caspase-11 has been proposed to mediate a protective role in the host during the acute phases of colitis, it appears to be detrimental in chronic inflammation, where it is significantly upregulated and promotes IL-1β and IL-18 release." (PMID 28179906, 2017). "Moreover, blocking IL-1β and IL-1865–67 or inhibiting caspase-168, 69 effectively protected mice against colitis." (PMID 28701727, 2017). "MPO activity, the TNF-α level, and the IL-1β level in the colitis rats were significantly higher than those in the control rats, and these effects were attenuated by acupuncture treatments at a neurogenic spot (Neuro-Sp), but not by stimulation of a nearby non-neurogenic site (Nearby site)." (PMID 29123119, 2017). "Furthermore, when Nlrp3R258W mice were crossed to an Il1r1−/− background to abolish the IL-1β signaling, these mice regained susceptibility to DSS-induced colitis." (PMID 29196621, 2017). "Furthermore, pharmacological inhibition of IL-1β was shown to successfully alleviate intestinal inflammation in colitis animal models." (PMID 28553294, 2017). "Moreover, colonic pro-inflammatory cytokines (TNF-α, IL-6, and IL-1β) induced by colitis were dramatically decreased by magnolol." (PMID 28726741, 2017). "In response to induction of colitis, expression of IL-1β increased." (PMID 27966619, 2016). "In contrast to IL-18, less attention has been focused on the role of IL-1β in colitis." (PMID 27966619, 2016). "Moreover, the M2-BMDM recipient mice possessed less IL-6, TNF-α, and IL-1β in the serum than the colitis-only control mice." (PMID 27094081, 2016). "Induction of colitis significantly increased mucosal concentration of IL-1β in the colon." (PMID 26798415, 2016). "Along the same lines, the role of IL-1β in colitis is also controversial." (PMID 27034589, 2016). "Furthermore, pharmacological inhibition of IL-1β or Caspase-1 was shown to successfully ameliorate intestinal inflammation in colitis animal models." (PMID 27965665, 2016).
colitis (continued). "Our present study has shown that induction of colitis by enema with acetic acid leads to a seven-fold increase in mucosal concentration of IL-1β in the colon at the seventh day after induction of colitis, followed by reduction in mucosal level of IL-1β during subsequent recovery." (PMID 27598133, 2016). "Induction of colitis increased mucosal concentration of IL-1β and TNF-α." (PMID 27598133, 2016). "Interestingly, treatment with bismuth significantly improved the colitis scores in A. parvulum-colonized mice and prevented expression of Il1β, Il12p40 and Cxcl1 messenger RNA (mRNA)." (PMID 27876802, 2016). "In addition, IL-1β-treated MSCs improved their ability to migrate to the spleen, mesenteric lymph nodes, and colon in the experimental model of colitis in mice and contributed to the reduction of the number of M1 macrophages in the murine peritoneal cavity." (PMID 27822228, 2016). "Finally, we evaluated the level of IL-1β and TNF-α in colon tissues, and found a significant decrease of IL-1β and TNF-α in TLR4 deficient mice compared to control 7 days after the initiation of colitis." (PMID 27105524, 2016). "Because exogenous IL-1β ameliorated OXA-induced colitis, this increase in IL-1β expression may be insufficient for prevention of overexpression of Th2 cytokines." (PMID 27966619, 2016). "Additionally, ELISA showed that the serum levels of IFN-γ, TNF-α, IL-12, IL-6, and IL-1β were down-regulated in a TNBS model of colitis." (PMID 26561804, 2015). "Relative to healthy mice, IL-1β immune-labelling increased under conditions of untreated colitis." (PMID 26218284, 2015). "Thus, the gastrointestinal bacterial endotoxin LPS is able to increase plasma TNF-α and IL-1β levels by the activation of the low-grade inflammatory signaling pathways, leading to chronic inflammatory diseases such as colitis and rheumatism." (PMID 25689583, 2015). "Furthermore, pretreatment with IL‐1β has been shown to enhance the therapeutic efficacy of MSC transplantation in a mouse model of colitis, when compared with naive cells." (PMID 26124062, 2015). "In our study, we found that the mRNA levels of TNF-a and IL-1β increased in the DSS colitis mice." (PMID 25762375, 2015). "Since IL-1β is involved in the early stage of DSS-induced colitis, the downregulation might be available for the treatment of patients with UC." (PMID 25120575, 2014). "We found that XLS treatment significantly reduced IL-1β production in DSS-induced colitis, a finding that could indicate that XLS prevents neutrophil and macrophage infiltration." (PMID 25120575, 2014). "In addition, the mRNA expression of several cytokine/chemokine (IL-6, CXCL1, CCL11, and IL-1β) genes was low in Eng+/− mice at days 18–23 of colitis." (PMID 25114380, 2014). "In addition, three days of oral Rb1 treatment potently inhibited the expression of TNF-α and IL-1β in the inflamed colon of mice with colitis." (PMID 24675731, 2014). "Pro-tumorigenic cytokines such as IL-1β, IL-6 and MIP-2 production as well as INF-γ and TNF production at the lamina propria were increased in the setting of colitis, and further in tumor tissues in associations with up-regulated TNFR2 and MLCK expressions in the epithelial cells of a CAC model." (PMID 24520376, 2014). "Development and remission of DSS-induced colitis in mice was determined by weight measurements and histology scores, and by quantification of expression of pro- (IL-1β, IL-6 and IFNγ) and anti-inflammatory (IL-10) cytokines, the chemokine CXCL1 and the inducible nitric oxide synthase." (PMID 24401855, 2014). "Investigation of the production of IL-1β and IL-6 in colitis mice serum confirmed our results." (PMID 24504372, 2014).
colitis (continued). "IL-1β plays a pro-inflammatory role, as its neutralization by either endogenous or exogenous administration of IL-1R antagonist results in significant amelioration of colitis." (PMID 25071778, 2014). "In concordance with the TNBS-colitis model, both IL-1α and IL-1β are elevated in IBD." (PMID 23382912, 2013). "Of these, all but IL-1β were increased in tissues with active vs. quiescent colitis." (PMID 24367513, 2013). "Compared with the traditional method to monitor IL-1β gene expression in DSS induced experimental colitis, bioluminescence is an interesting technology that may be used to evaluate transcription of various genes in real time in experimental colitis." (PMID 23577872, 2013). "In this model, both IL-1α and IL-1β are increased in the inflamed intestinal tissues and display pro-inflammatory properties, as neutralization by either endogenous or exogenous IL-1Ra administration resulted in significant amelioration of colitis." (PMID 23847622, 2013). "TNF-α and IL-1β involved in the development of DSS-induced colitis in mice." (PMID 23159923, 2012). "Other factors that may be involved in the inflammatory process in human IBD as well as in DSS colitis include pro-inflammatory cytokines such as interleukin (IL)-1β and TNF-α." (PMID 22562255, 2012). "Liver responses detected in infected animals at 3 DPI overlapped many targets associated with acute colitis and disease severity including MCP-1, MIP-1α, MIP-1β, RANTES, and KC and neutrophil/Th17-related targets such as KC, IL-1β, IL-6, IL-12/23p40, and G-CSF." (PMID 22427959, 2012). "Our findings that L-Arg also effectively reduced other proinflammatory mediators, such as the innate immune cell products IL-1α, IL-1β, and IL-6, as well as the prototype Th17 cytokine, IL-17, suggest that it may be broadly beneficial in colitis." (PMID 22428068, 2012). "In contrast, IL-1β mRNA expression increased even in the early phase of the colitis." (PMID 23209802, 2012). "The levels of TNF-α and IL-1β were significantly raised in DSS-induced colitis." (PMID 23159923, 2012). "Since both MIF and IL-1β induce neutrophil recruitement, and that blockade of MIF activity down-regulates IL-1β, it is likely that the decrease of neutrophil influx and IL-1β release in the inflamed areas would result from FSG-mediated inhibition of MIF production in the acute phase of colitis." (PMID 23166707, 2012). "When used to treat colonic inflammation induced by TNBS administration to Balb/c mice, ciprofloxacin effectively protected against development of local signs of colitis and markedly reduced local generation of inflammatory mediators including IL-1β, IL-6, IFNγ and TNFα." (PMID 22046243, 2011). "Confirming the protective anti-inflammatory effect of n-3 PUFAs, transgenic fat-1 mice expressing a gene encoding an n-3 fatty acid desaturase which enables production of n-3 from n-6 PUFAs, exhibit low NFκB activity, reduced levels of TNFα and IL-1β, and are protected from colitis." (PMID 20122166, 2010). "The anti-inflammatory effects of diverse combination of thyme (p-cymene and thymol as main components) and oregano (carvacrol as major component) oils on mice with TNBS-induced colitis showed that some combinations lowered the amounts of IL-1β and IL-6 cytokines." (PMID 21160452, 2010). "In contrast, pre-treatment with Bb-CM by i.p. route induced a significant protection against colitis (WS = 1.7±0.8, 62% protection) and a statistically significant decrease in pro-inflammatory cytokine expression [IL-1β, CXCL1 (equivalent to human IL-8), COX2, IL-23, IL-6]." (PMID 19381276, 2009). "Finally, we have shown that Card15/Nod2 invalidation exacerbates the severity of TNBS induced colitis, as evidenced by the increase in all parameters characterising colonic inflammation (damages scores and mucosal levels of IL-1β, TNFα and IL-12)." (PMID 17565376, 2007).
colitis (continued). "Examination of IL-1β and IL-6 protein expression in our experimentconfirmed the best efficacy of the medium dose of thyme and oregano oilcombination in the suppression of colitis." (PMID 18288268, 2007). "As well, WT(PFKFB3fl/flLyz2-Cre) mice developed less severe colitis compared to WT(PFKFB3fl/fl) groups, showing reduced weight loss, lower DAI scores, longer colon length, diminished histopathology and intestinal damage, and lower inflammatory cytokine levels of Il1β, Il6, and Tnfα." (PMID 41378888, 2026). "Treatment with the selective TAAR1 antagonist EPPTB substantially improved colitis symptoms, including reduced weight loss, lower DAI scores, prevention of colon shortening, diminished tissue damage, and decreased expression of pro-inflammatory cytokines (TNF-α, IL-6, and IL-1β) in colonic tissue." (PMID 41550498, 2026). "Hence, to further dissect the protective effect of the combined treatment of vitamin C/allicin on DSS-induced colitis in mice, we quantified the relative gene expression levels of inflammation-related cytokines IL-1β, IL-6, and TNF-α in the middle and posterior segments of the colon." (PMID 40077487, 2025). "This is particularly relevant as Gram-negative bacteria, including enterobacteria, are major LPS producers, and their reduction may lower susceptibility to colitis and attenuate inflammatory responses mediated by proinflammatory cytokines such as TNF-α and IL-1β." (PMID 40141446, 2025). "Based on human UC biopsy sample examination and an animal model of colitis (induced by dextran sulfate sodium - DSS in CHGA gene knockout mice), a positive correlation between CgA and M1 macrophage-associated pro-inflammatory cytokines such as IL-1β, IL-6, and TNF have been observed." (PMID 40370467, 2025). "Quinic acid treatment could alleviate the symptoms of dextran sodium sulfate (DSS)-induced colitis in mice, maintain the intestinal barrier, down-regulate the expression of inflammatory factors such as IL-1β and TNF-α, and inhibit the activation of the MyD88/NF-κB signaling pathway." (PMID 40647020, 2025). "Additionally, the aggravation of colitis by sorbitol was dependent on IL-1β." (PMID 40678521, 2025). "In vivo studies using a DSS-induced colitis mouse model further demonstrated that HME-MUL-F2 could alleviate colitis symptoms, increase body weight and colon length, reduce pro-inflammatory cytokines (IL-1β, TNF-α, IL-6, MCP-1), and increase anti-inflammatory cytokines (IL-10)." (PMID 40283912, 2025). "Taking into account previous data that our tested substances, mainly 13b and 7b, serve as COX-2 inhibitors, we decided to investigate whether TNBS-induced colitis model may generate an inflammatory response in the testes and what impact the studied substances have on the testicular level of IL-1β." (PMID 40283981, 2025). "Additionally, DSS-induced colitis mice show enhanced IL-1β level produced by NLRP3 inflammasome." (PMID 38417794, 2024). "In addition, RT-qPCR and the ELISA assay demonstrated that the pro-inflammatory cytokines of TNF-α, IL-1β, and IL-6 increased in number in the colitis tissues and sera, whereas UTI could reverse this pro-inflammatory phenotype." (PMID 38397811, 2024). "This study showed that both OBB and BBR can increase the abundance of Bacteroides, and OBB has superior anti-colitis activities, including improving the intestinal mucosal barrier, inhibiting colitis tissue damage, and reducing pro-inflammatory factors such as IL-6, IL-1β, IL-17, TNF-α and IFN-γ." (PMID 38660314, 2024). "To verify our hypothesis that IA-0130 suppresses the excessive expression of pro-inflammatory cytokines, we analyzed the mRNA and protein expression of pro-inflammatory cytokines, TNF-α, IL-1β, IL-6, and IL-17A, which are important in colitis development and maintenance." (PMID 38916850, 2024).